TAL1 (TAL bHLH transcription factor 1, erythroid differentiation factor)
Diseases named in the same sentence as TAL1 in open-access papers (continued):
Sharing a sentence is not in itself a finding about the gene and the disease.
leukemia (continued). "Moreover, confirming the direct binding of TAL1 isoforms and NOTCH1 effectors to TSPAN32 regulatory elements, as well as determining the functional impact of TSPAN32 reactivation on leukemia cell behavior, will be critical next steps." (PMID 41007654, 2025). "In Tal1-Lmo1 transgenic mice, T-LICs are found in both the CD4−CD8− double-negative (DN) and CD4+CD8+ double-positive (DP) populations in the thymus, even though the leukemic DN3 and DN4 populations have the highest leukemia-initiating potential." (PMID 36428753, 2022). "Finally, in a study of leukaemia patients, a small DNA insertion resulting in a TFBS for MYB created an enhancer near TAL1, which led to activation of this oncogene and the onset of leukaemia." (PMID 31937202, 2020). "Interestingly, previous studies have shown that the enhancer/promoter loop interactions required looping factor LDB1 and TAL1/GATA/LMO2 transcription super complexes that are present in both normal hematopoiesis and T-ALL leukemia." (PMID 32086528, 2020). "As none of the healthy controls have a history of leukemia, it is highly likely that these TAL1 fusions are passenger fusions." (PMID 32414213, 2020). "On the other hand, UTX was identified as a prooncogenic cofactor essential for leukemia maintenance in class II basic helix–loop–helix (bHLH) protein TAL1-positive (but not TAL1-negative) T-cell acute lymphoblastic leukemia." (PMID 29351209, 2018). "For example, GATA1 partners with HNF1 in hematopoietic progenitor cells; with PPARA:RXRA in leukemia; with SRF, CDX and FOXP3 in primary T-cells; with SRY, NKX2-1, FOXF1, OCT4 and ZBTB16 in differentiated ESCs and with TAL1:TCF3 motif co-occurring in various fibroblasts." (PMID 30142147, 2018). "Therefore, our finding that hematopoietic transcription factors, such as TAL1 and RUNX1, influence expression of PRKACB isoforms could connect aberrant transcription factor function with altered PKA signalling in leukemia." (PMID 29069738, 2017).
T-cell acute lymphoblastic leukemia (62 papers, 2009 to 2025). Acute lymphoblastic leukemia of T-cell origin. "The immunophenotypic distribution according to fusion gene status followed expected patterns, with TEL::AML1, BCR::ABL, E2A::PBX1 and MLL::AF4 fusions exclusively associated with B-cell ALL and SIL::TAL1 fusion predominantly found in T-cell ALL." (PMID 41234729, 2025). "The only SIL::TAL1-positive patient had a T-cell immunophenotype, consistent with the known association of this fusion gene with T-cell ALL." (PMID 41234729, 2025). "For instance, in T-cell acute lymphoblastic leukemia, somatic mutations create a SE upstream of the TAL1 oncogene." (PMID 36224576, 2022). "TAL1 is also implicated as a key transcriptional factor involved in the development of T-cell acute lymphoblastic leukemia." (PMID 32414213, 2020). "Recurrent mutations at an enhancer 8 kb upstream of the TAL1 proto-oncogene were discovered in T-cell acute lymphoblastic leukemia (T-ALL) cell lines and patients." (PMID 31980609, 2020). "Aberrant expression of TAL1 in later stages of T-cell development is associated with the development of T-cell acute lymphoblastic leukemia (T-ALL)." (PMID 30691465, 2019). "Another gene, named TAL1, was reported to be associated with outcome of T-cell acute lymphoblastic leukemia." (PMID 27903973, 2017). "The transcription factor TAL1 is a proto-oncogene whose aberrant expression in committed T-cell precursors is associated with the development of T-cell acute lymphoblastic leukemia (T-ALL)." (PMID 26882564, 2016). "Furthermore, uncontrolled TAL1 expression is associated with T-cell acute lymphoblastic leukemia in humans." (PMID 40342930, 2025). "In T-cell acute lymphoblastic leukemia, heterozygous somatic mutations of T-cell acute lymphocytic leukemia protein 1 (TAL1) oncogene are acquired, which introduce binding motifs for the TF myeloblastosis oncogene and creates a SE upstream of the TAL1 oncogene." (PMID 38481812, 2024). "In addition, aberrant activation of Tal1, another bHLH inhibitor of E proteins, is the most common cause of human pediatric T cell acute lymphoblastic leukemia (T-ALL)." (PMID 19688092, 2009). "In TAL1-positive T-cell acute lymphoblastic leukemia (T-ALL) cell lines, the TAL1 complex aberrantly activates SEs within the ARID5B locus, contributing to the development of T-ALL." (PMID 40895527, 2025). "In the context of T-cell acute lymphoblastic leukemia (T-ALL), the overexpression of TAL1 is closely associated with the formation of SEs." (PMID 40083704, 2025). "miR-7 can directly bind to the 3′ UTR of T-cell acute lymphocytic leukemia protein 1 (TAL1) to suppress the migration, invasion, and cell motility of T-cell acute lymphoblastic leukemia cells, which can be reversed by TAL1 overexpression." (PMID 38632598, 2024). "For example, small noncoding insertions introducing MYB motifs upstream of TAL1 gene in patients with T-cell acute lymphoblastic leukemia (T-ALL) were found to generate a TAL1-activating SE through MYB and cofactor recruitment." (PMID 38844984, 2024). "TAL1 is also known to control normal myeloid differentiation and is an experimental drug target for the treatment of T-cell acute lymphoblastic leukemia." (PMID 36902378, 2023). "INDELs acquired upstream of the TAL1 oncogene introduce de novo binding motifs for the TF MYB, which creates a SE and drives TAL1 overexpression in primary patient T-cell acute lymphoblastic leukemia (T-ALL)." (PMID 37548349, 2023). "The basic helix-loop-helix proteins TAL1, LYL1 and the LIM-only protein LMO2 were identified from the breakpoints of chromosomal translocations associated with T cell acute leukemia." (PMID 35508511, 2022). "For example, an insertion of a small DNA sequence that recruits transcription factor Myb upstream of the Tal1 gene locus creates a super-enhancer that drives high level Tal1 expression in T-cell acute lymphoblastic leukemia." (PMID 36012554, 2022).
T-cell acute lymphoblastic leukemia (continued). "For example, the oncogenic TF TAL1 can produce a modified autoregulatory circuitry that drives the oncogenic program in T-cell acute lymphoblastic leukaemia." (PMID 33902514, 2021). "TAL1 (or SCL) is a class II bHLH transcription factor first described as a master oncogenic driver of T-cell acute lymphoblastic leukemias (T-ALL)." (PMID 34771555, 2021). "For example, non-coding mutation hotspots upstream of TAL1 and LMO1 in T-cell acute lymphoblastic leukemia lead to the formation of de novo MYB binding sites that drives the overexpression of TAL1 and LMO1 oncogenes." (PMID 32550006, 2020). "The haematopoietic transcription factor TAL1 (T-cell acute lymphoblastic leukaemia) exerts an important function in embryonic HSC development and also at the megakaryocytic/erythroid branching in the adult organism." (PMID 30653565, 2019). "A recent study demonstrated that KDM6A is a co-activator of the oncogenic transcription factor TAL1 and is essential for disease progression of TAL1-positive T-cell acute lymphoblastic leukemia (T-ALL)." (PMID 28717873, 2018). "Previous results indicated that miR-146b-5p is downregulated by TAL1, a transcription factor critical for early hematopoiesis that is frequently overexpressed in T-cell acute lymphoblastic leukemia (T-ALL) where it has an oncogenic role." (PMID 27550837, 2016). "Early studies have suggested that mouse and human Drg1 interacts in vitro and in vivo with the oncogenic T-cell acute lymphoblastic leukemia (Tal1/Scl) protein, a basic helix–loop–helix (bHLH) transcription factor involved in cell growth and differentiation." (PMID 23002146, 2012). "TAL1 is required for normal haematopoiesis; its aberrant expression leads to T-cell acute lymphoblastic leukaemia." (PMID 19536094, 2009). "As TAL1 OE is a common cause of T-cell acute lymphoblastic leukemia (T-ALL), it is not surprising that Doxy (+) Tet-TAL1 iPSCs exhibited higher differentiation into other hematopoietic cells." (PMID 40342930, 2025). "However, UTX appears to play an oncogenic role in breast cancer and TAL1-driven T-cell acute lymphoblastic leukemia." (PMID 37692474, 2024). "Using T-cell acute lymphoblastic leukemia (T-ALL) as an example, we show that patients harboring 5'super-enhancer (5'SE) mutations of the TAL1 oncogene identifies a specific patient subgroup with poor prognosis irrespective of the level of oncogene dysregulation." (PMID 36650499, 2023). "In erythroid differentiation, core transcriptional networks play crucial roles, which include gata binding protein 1 (GATA1), T-cell acute lymphoblastic leukemia/stem cell leukemia (TAL1/SCL), Krüppel-Like Factor 1 (KLF1), LIM domain only 2 (LMO2), and LIM domain binding protein 1 (LDB1)." (PMID 37296674, 2023). "Furthermore, it was shown to act as a co-activator of Tal1, a key transcriptional regulator in the development of T-cell acute lymphoblastic leukaemia." (PMID 35603697, 2022). "Most oncogenes identified in T-cell acute leukemia (T-ALL) encode factors either regulating stage-specific thymocyte development, comprising NOTCH1, LMO2 and HOXA genes, or ectopically activated factors, including TAL1 and NK-like homeobox genes (NKLs)." (PMID 19835636, 2009). "For example, one subtype of T cell acute lymphoblastic leukemia (T-ALL) arises from somatic mutations at noncoding sites upstream of the TAL1 gene in which a binding site of transcription factor MYB is imported, thus forming an SE and, finally, resulting in the overexpression of TAL1." (PMID 40672386, 2025). "In T-cell acute lymphoblastic leukaemia (T-ALL) lacking TAL1d abnormality or TAL1 chromosomal rearrangements, heterozygous indel mutations in the region 7.5 kb upstream of TAL1 TSS result in de novo MYB binding motif (or even two motifs as in Jurkat cells) and thereby the emergence of TAL1-SE." (PMID 38542080, 2024).
T-cell acute lymphoblastic leukemia (continued). "Current models suggest that RUNX1 cooperates with other oncogenic factors (e.g., NOTCH1, TAL1) to drive the expression of proto-oncogenes in T cell acute lymphoblastic leukemia (T-ALL) but the molecular mechanisms controlled by RUNX1 and its cooperation with other factors remain unclear." (PMID 37213235, 2023). "In T-cell acute lymphoblastic leukemia (T-ALL), a 2–18 bp fragment is inserted into the noncoding intergenic region of the TAL1 gene to create a de novo binding site for MYB, thereby initiating SE formation and increasing TAL1 expression." (PMID 37501079, 2023). "As an example, deletion of a CTCF binding site insulating the promoter of TAL1 gene from regulatory elements adjacent to the CMPK1 promoter was shown by CRISPR/Cas9 experiments to cause activation of TAL1, an oncogenic driver of T cell acute lymphoblastic leukemia." (PMID 31362752, 2019). "Likewise, FOXP3 downregulation attenuated the expression of LIM Domain Only 2 (LMO2) but increased the expression of an oncogenic transcription factor T-cell acute lymphocytic leukemia protein 1 (TAL1) at mRNA level in T-cell acute lymphoblastic leukemia (T-ALL) cells." (PMID 31815635, 2019). "An example of this occurs in T-cell acute lymphoblastic leukemia (T-ALL) where a mutation in a CTCF anchor motif disrupts the insulated neighborhood where the T-ALL-associated oncogene, TAL BHLH transcription factor 1 (TAL1), resides." (PMID 30268153, 2018). "However, TAL1 is ectopically expressed in a majority of childhood T-cell acute lymphoblastic leukemia (T-ALL) cases, with increased TAL1 transcript levels found in more than 60% of T-ALL patients even in the absence of obvious genetic alterations in the gene locus." (PMID 26882564, 2016). "The SIL::TAL1 (STIL::TAL1) fusion gene, typically resulting from a submicroscopic interstitial deletion of chromosome 1p32, is predominantly observed in T-cell ALL and occurs in approximately 10%–30% of pediatric T-ALL cases." (PMID 41234729, 2025). "RUNX1 and other hematopoietic TFs, TAL1/SCL, GATA2, PU.1, LMO2 and LDB1 bind at RUNX1-SE, which is observed in normal HSCs and T-cell acute lymphoblastic leukemia cells, regulate HSCs differentiation and development." (PMID 39090713, 2024). "This study reveals the crucial role of splicing in TAL1 isoform regulation and its impact on hematopoiesis; enhancers regulate alternative splicing of TAL1 exon 3, and modulation of TAL1 isoform ratio may represent a promising therapeutic approach for T-cell acute lymphoblastic leukemia." (PMID 37379322, 2023). "Mice, bearing human oncogenes TAL BHLH Transcription Factor 1 (TAL1; SCL) or LIM Domain Only 1 (LMO1), responsible for T-cell acute lymphoblastic leukemia (T-ALL) development, were crossed with BCL11B floxed and with CRE-ER/lox mice." (PMID 35563322, 2022). "In T-cell acute lymphoblastic leukemia, an insertion in the TAL1 locus creates a new binding site for MYB, with the subsequent formation of a new SE that drives TAL1 overexpression." (PMID 34680347, 2021). "MiR-448 is downregulated in T-cell acute lymphoblastic leukemia (T-ALL) and seems to target the principal proto-oncogene (TAL1) of this disease." (PMID 32992819, 2020). "In human T-cell acute lymphoblastic leukemia (T-ALL) cells, a CRISPR-Cas9 editing tool was used to disrupt TAL1 (SCL) or TRIB1 (TRB1) genes to delineate their biological functions." (PMID 30016959, 2018). "In human T cell acute lymphoblastic leukemia (T-ALL), NOTCH, PITX and TAL1 are also found to up-regulate TRIB2." (PMID 30541550, 2018). "Trib2 is highly expressed in human T cell acute lymphoblastic leukemia (T-ALL) and is a direct transcriptional target of the oncogenic drivers Notch and TAL1." (PMID 27191957, 2016).
T-cell acute lymphoblastic leukemia (continued). "In T-cell ALL, up to 22 different oncogenes have been identified as TCR translocation partners; the LMO2, TAL1, and TLX1 genes were most frequently involved in these rearrangements and the majority of all TCR translocations involved the TRD locus." (PMID 25515027, 2014). "In T cell acute lymphoblastic leukemia (T-ALL), small insertions of 2–18 bp in the noncoding intergenic region upstream of the TAL1 oncogene produce de novo binding sites for the transcription factor MYB, resulting in SE formation to drive TAL1 expression." (PMID 32382065, 2020).
acute lymphoblastic leukemia (47 papers, 2009 to 2026). Leukemia with an acute onset, characterized by the presence of lymphoblasts in the bone marrow and the peripheral blood. "Overexpression of TAL1 (T-cell acute lymphoblastic leukemia transcription factor, TAL1) in a subset of acute lymphoblastic leukemia (ALL) is associated with SE formation." (PMID 32128448, 2020). "Aberrant overexpression of the TAL1 oncogenic transcription factor is found in ~50% of T cell acute lymphoblastic leukemias (T-ALL) and is associated with less favorable outcomes." (PMID 40479062, 2025). "Approximately 60% of T-ALL cases also have mutations that augment expression of the transcription factors T acute lymphoblastic leukemia antigen 1 (TAL1), also called Stem Cell Leukemia (SCL), and lymphocytic leukemia antigen 1 (LYL1)." (PMID 35514954, 2022). "Heterozygous somatic mutations have been shown to produce binding sites for the MYB transcription factor upstream of the TAL1 oncogene in acute lymphoblastic leukemia (ALL)." (PMID 40581650, 2025). "In acute lymphoblastic leukemia (ALL), heterozygous somatic mutations have been observed to create binding sites for the MYB transcription factor upstream of the TAL1 oncogene." (PMID 38374872, 2024). "The HLH (helix loop helix) TF (transcription factor) family contains key regulators of lymphocyte development and maturation, such as Tal1 (T-cell acute lymphoblastic leukemia 1)/SCL (stem cell leukemia)/TCL5 (T-cell leukemia/lymphoma 5)." (PMID 35958877, 2022). "The pan-cancer study reported mutation in SIX1, TAL1, and ID4 were present in the Wilms Tumors, T-lineage acute lymphoblastic leukemias, and B-lineage acute lymphoblastic leukemias, respectively." (PMID 31681566, 2019). "Furthermore, aberrant expression of TAL1 in the T-cell compartment caused by chromosomal translocations leads to T-lineage acute lymphoblastic leukemia (T-ALL)." (PMID 29069738, 2017). "A cohort of 165 adult T-ALL treated prospectively in the GRAALL (Group for Research in Adult Acute Lymphoblastic Leukaemia) trial was split into TAL1 expression quartiles, and compared for disease-free (DFS) and overall survival (OS)." (PMID 25615415, 2015). "To test whether the Random Forest CRM models may be suitable to identify cancer driver mutations we examined in detail a recently published cis-regulatory mutation in the TAL1 promoter in T-cell Acute Lymphoblastic Leukemia (T-ALL)." (PMID 26562774, 2015). "Recently two cancer-related CRM mutations have been discovered, namely: a highly recurrent mutation in the TERT promoter that is found in many cancer types; and a more distally located enhancer mutation upstream of the TAL1 gene in T-cell acute lymphoblastic leukemia (T-ALL)." (PMID 26562774, 2015). "We applied our application to analyze RNA-seq data generated from a USP7 knockdown in T-cell acute lymphoblastic leukemia (T-ALL) cell line, which identified upregulated expression of a TAL1-associated proliferative signature in T-cell acute lymphoblastic leukemia cell lines." (PMID 35205126, 2022). "Genomic rearrangements of the human MYB gene and mutations that create de-novo MYB binding sites in transcriptional control regions of the TAL1 and LMO1 oncogenes have been detected in acute lymphoid leukemia, suggesting that MYB plays causal roles in the development of these leukemias." (PMID 30177851, 2018). "T-cell acute lymphoblastic leukemia 1 (TAL1, also known as stem cell leukemia, SCL) is a frequent target for chromosomal translocation, interstitial deletion, or mutation in T-ALL." (PMID 24040098, 2013). "Mansour and colleagues dissected the molecular mechanisms by which a short 12‐bp insertion approximately 8 kbp upstream of the TAL1 oncogene introduces novel binding sites for the transcription factor MYB, and establish a new super‐enhancer in a subset of acute lymphoblastic leukemia (ALL) cases." (PMID 33502116, 2021).
acute lymphoblastic leukemia (continued). "In T‐cell acute lymphoblastic leukemia (T‐ALL), a deletion of the boundary between the TAL1‐ and STIL loci disrupts a CTCF site, placing the TAL1 oncogene under control of an enhancer outside its neighborhood." (PMID 39853740, 2026). "In both B-cell and T-cell acute lymphoblastic leukemia (ALL), SEs dysregulation drives transformation by overexpressing oncogenes like MYC and TAL1, often through alterations in lineage-specific transcription factors." (PMID 41268574, 2025). "In T‐cell acute lymphoblastic leukemia (T‐ALL), specific non‐coding mutations upstream of the TAL1 oncogene are capable of generating a self‐sustaining transcriptional loop, which involves several T‐ALL transcription factors such as MYB, GATA3, RUNX1 and TAL1 itself." (PMID 27756687, 2017).